CTHRC1 (collagen triple helix repeat containing 1)
Diseases named in the same sentence as CTHRC1 in open-access papers (continued):
Sharing a sentence is not in itself a finding about the gene and the disease.
cancer (114 papers, 2007 to 2026). A tumor composed of atypical neoplastic, often pleomorphic cells that invade other tissues. "Single-cell data reveal an upregulated expression of the invasive gene set in CTHRC1-positive cancer associated fibroblasts (CAFs), thereby modulating their interaction with M2-type macrophages." (PMID 40134434, 2025). "CTHRC1 is also instrumental in immune escape by driving the remodeling of the extracellular matrix through interactions with cancer-associated fibroblasts." (PMID 40201173, 2025). "Accordingly, CTHRC1 was identified as a novel oncogene aberrantly overexpressed in various malignant tumors, exhibiting associations with bone metastasis and unfavorable patient outcomes." (PMID 38891078, 2024). "It was observed that miR-155 can impede the advancement and spread of CRC by suppressing CTHRC1 (collagen triple helix repeat containing 1), a protein associated with cancer growth." (PMID 39767565, 2024). "CTHRC1 specifically activated PSC into myofibroblast-like cancer-associated fibroblasts (myCAFs), which are characterized by a significantly upregulated POSTN gene expression." (PMID 37444482, 2023). "The overexpression of CTHRC1 in adult mesenchyme-derived cells is associated with enhanced cell motility and the invasiveness of cancer metastases." (PMID 37109608, 2023). "Additional interesting targets revealed in our datasets include CTHRC1, which has been linked to physiological and pathologic conditions, including cancer and fibrosis." (PMID 36531712, 2022). "Copy number variation and mutation analysis for CTHRC1 across cancers find it to be prominently amplified in most cancers including BRCA, HNSC and LIHC (marked by arrow)." (PMID 36190948, 2022). "Recent studies have shown that CTHRC1 is overexpressed in cancers and associated with poor prognosis." (PMID 36190948, 2022). "Fibro_2 cells were characterized by collagen (COL1A1, COL3A1) and cancer-associated fibroblast genes (CTHRC1, FAP)." (PMID 35935940, 2022). "In summary, our research is a preliminary study that reported the shared clinicopathological features-specific diagnostic and prognostic potential of CTHRC1 in six different cancers including HNSC, KIRC, LIHC, LUAD, STAD, and UCEC." (PMID 34615943, 2021). "In this study, our results further imply that CTHRC1 is associated with immune cell infiltration in various cancers." (PMID 34702252, 2021). "Based on the pan-cancer analysis, CTHRC1 mRNA and protein levels were linked to prognosis of patients with various cancers." (PMID 34702252, 2021). "Genetic alterations in CTHRC1 were dominated by “amplification” types, which were observed in almost all TCGA cancer cases, and the “mutation” type was the second most common." (PMID 34702252, 2021). "In the current study, we comprehensively analyzed CTHRC1 in distinct human cancer subtypes for the first time and find more closely CTHRC1-associated cancer subtypes through the integrated analyses approach." (PMID 34615943, 2021). "As an important component of the Wnt signaling pathway, CTHRC1 has been suggested to be involved in the biogenesis and progression of various cancers and is distinctly linked to the immune cell infiltration." (PMID 34702252, 2021). "The abnormal expression of CTHRC1, a regulator of matrix deposition, has been widely found across different solid cancers and is considered to be associated with cancer invasion and metastasis." (PMID 21060876, 2010). "Two cancer-associated fibroblast marker genes, CTHRC1 and POSTN, were clustered here." (PMID 39850884, 2024). "However, the knockout of the POSTN gene caused the PSC-conditioned media to completely lose its cancer migration/invasion-promoting effects in response to the stimulation of CTHRC1." (PMID 37444482, 2023). "CTHRC1, a secreted protein, has been found to be implicated in a series of physiological and pathological processes, including inflammatory arthritis, vascular remodeling, bone formation, and cancer development." (PMID 34512149, 2021).
cancer (continued). "Furthermore, high CTHRC1 expression is observed in many types of cancer and is associated with cancer metastasis to the bone and poor patient prognosis." (PMID 33670905, 2021). "Therefore, we evaluated the associations of CTHRC1 expression with the levels of immune cell infiltration in 39 cancer cases." (PMID 34702252, 2021). "Therefore, the main aim of our study is to comprehensively investigate CTHRC1 in distinct other subtypes of human cancers and find more closely CTHRC1-associated cancer subtypes through an integrated analyses approach." (PMID 34615943, 2021). "Furthermore, invasive cancer cells express CTHRC1 and high CTHRC1 expression in tumors is associated with poor prognosis." (PMID 32317643, 2020). "We have demonstrated that high levels of CTHRC1 are closely correlated with clinical stage of FIGO classification and prognosis of EOC, suggesting that CTHRC1 serves as a candidate cancer biomarker for the recurrence risk and prognosis in post-operative EOC patients." (PMID 26452130, 2015). "Although it is still unclear whether CTHRC1 has any function in carcinogenesis, several reports have suggested that inflammation and tissue repair are tightly linked with the development of cancer." (PMID 24841500, 2014). "Collagen triple helix repeat containing 1 (CTHRC1) is a secreted protein that has previously been explored for its role in tissue remodeling and cancer." (PMID 42191349, 2026). "The focused heatmap of the top 10 DEGs highlighted genes such as TPX2, MKI67, EXO1, and CTHRC1, which showed progressive upregulation from infection to cancer." (PMID 40445003, 2025). "Collagen triple helix repeat containing 1 (CTHRC1) is a secreted protein involved in tissue remodeling and fibrotic processes, which also suggests emerging roles in cancer." (PMID 40751418, 2025). "Genes such as TPX2, MKI67, EXO1, and CTHRC1 exhibited progressive upregulation from infection to cancer, highlighting involvement in cell cycle regulation, DNA repair, and extracellular matrix remodeling." (PMID 40445003, 2025). "Collagen triple helix repeat containing 1 (CTHRC1) has been shown to be highly expressed in various cancers." (PMID 38937712, 2024). "Future studies will need to be conducted not only in PDAC, but in other cancers to validate the potential of CTHRC1 as a defining marker in myCAF." (PMID 39075108, 2024). "A contrasting pattern of similarity emerges among carcinomas originating from uterine, pulmonary, and hepatic tissues, where genes like CTHRC1, ADH1B, GHR, DES, SFRP1, and RNF150 share similar weights." (PMID 39596491, 2024). "The molecular mechanisms of the autocrine action of CTHRC1 include increasing the adhesion of cancer cells to the extracellular matrix (ECM) through the induction of integrin β1 expression and the activation of focal adhesion kinase." (PMID 37444482, 2023). "CTHRC1 is a vital oncogene; its expression of collagen triple helix repeat containing protein 1 is a cancer-related protein." (PMID 37938417, 2023). "CTHRC1 (Collagen triple helix repeat containing 1) is another ECM protein that is thought to play a significant role in cancer development." (PMID 36982551, 2023). "In the first proliferation study, cancer cells were treated directly by PBS or CTHRC1 and also by conditioned media." (PMID 37444482, 2023). "Cancer cells release CTHRC1 into their microenvironment, enhancing their motility and the motility of neighboring cancer cells by activating RhoA signaling." (PMID 37273536, 2023). "PSC-mediated CTHRC1 cancer proliferation-promoting effects were completely reversed by the anti-CTHRC1 antibody in both cell lines." (PMID 37444482, 2023). "The reduced expression of CTHRC1 in FOLFIRI responders would make these patients’ cancer more sensitive to chemotherapy." (PMID 38304289, 2023).
cancer (continued). "A recent study demonstrated that the patients’ overall survival time was considerably shortened (p > 0.05 in Kaplan–Meier plotter) when their CTHRC1 transcriptional level was greater in various cancers." (PMID 37109608, 2023). "Periostin, a stroma-specific molecule, demonstrated an essential role in the CTHRC1–PSCs–cancer metastasis axis." (PMID 37444482, 2023). "CTHRC1 was much more extensively expressed by fibroblast cells than cancer cells, immune cells, and endothelial cells, and other stromal cells had a much lower CTHRC1 expression." (PMID 37444482, 2023). "Periostin, a stroma-specific molecule coded by the gene POSTN, was found to have a central role in the CTHRC1–PSC–cancer metastasis axis." (PMID 37444482, 2023). "This identified 3 matrisome genes, CTHRC1, PDGFA and IL7 to be prominent candidates of which only CTHRC1 was upregulated in pan-cancer and 3 individual cancers making it the matrisome gene of interest." (PMID 36190948, 2022). "We also compared the effect CTHRC1 has on survival in 30 cancers using univariate and multivariate analysis." (PMID 36190948, 2022). "The TIMER database was utilized to investigate the association between COL8A1, COL10A1, CTHRC1, and FAP, and immune cell infiltration, as immune cell levels correlate with the proliferation and progression of cancer cells." (PMID 35910202, 2022). "It would hence be of interest to look at the protein expression data in cancers for CTHRC1 and the now identified genes of interest, POSTN, MMP13, SFRP4, ADAMTS16 and FNDC1." (PMID 36190948, 2022). "This is consistent with other EMT pathway genes in the skin; COMP, CTHRC1, ECM2, FBN1, LOX, and SPARC were all upregulated in samples with a mutation in a cancer gene." (PMID 36531005, 2022). "This includes the 3 CTHRC1 overexpressing individual cancers (BRCA, HNSC and LIHC) identified earlier." (PMID 36190948, 2022). "CTHRC1, a regulator of collagen synthesis, was identified as the most prominently upregulated matrisome gene of interest across cancers." (PMID 36190948, 2022). "Cytohubba analysis of these genes revealed 13 hub genes, of which MMP13, POSTN, SFRP4, ADAMTS16 and FNDC1 were significantly altered in their expression with CTHRC1 and seen to affect survival across cancers." (PMID 36190948, 2022). "A similar analysis of matrisome genes in individual cancers identified CTHRC1 to be significantly altered." (PMID 36190948, 2022). "As revealed in recent years, CTHRC1 is upregulated in various tumors, and promote cancer cell invasion and migration, which also works as a potential biomarker of various cancers." (PMID 35313900, 2022). "In this study, the Cancer Genome Atlas (TCGA) and Oncomine database were employed to investigate the expression and function of CTHRC1 in COAD." (PMID 35307012, 2022). "Using TCGA data univariate analysis was done to calculate the hazards ratio (HR), which captures the likelihood of CTHRC1 expression affecting survival in cancers." (PMID 36190948, 2022). "The results showed that CTHRC1 mRNA levels in various cancer tissues were significantly higher than those in normal tissues." (PMID 35307012, 2022). "CTHRC1 was however the only gene that was affected in more than one individual cancer type (BRCA, HNSC and LIHC)." (PMID 36190948, 2022). "Our pan-cancer analysis of matrisome genes for copy number variation (amplification or deletion), relative expression and effect on cancer survival identified collagen triple helix repeat containing 1 (CTHRC1) as a major pan-cancer ECM regulator." (PMID 36190948, 2022). "Collagen triple helix repeat-containing (CTHRC1) was considered a cancer-related factor that sustains migration processes, proliferation, invasion, and metastasis in GC." (PMID 35328635, 2022).
cancer (continued). "Its role is further supported by CTHRC1 being identified as the most prominently regulated ECM protein across individual cancers." (PMID 36190948, 2022). "Therefore, this is the first study that reported the shared clinicopathological features-specific diagnostic and prognostic potential of CTHRC1 in six different cancers including HNSC, KIRC, LIHC, LUAD, STAD, and UCEC, which may provide new therapeutic possibilities for cancer patients." (PMID 34615943, 2021). "In the current study, we analyzed and validated the CTHRC1 expression variations in 24 different human cancer tissues paired with normal tissues using publically available databases." (PMID 34615943, 2021). "The results showed strong positive relationships between the expression of different ICP genes and CTHRC1 expression in many cancers, such as GBM, LGG, LUAD, etc.." (PMID 34702252, 2021). "Overall, these results confirmed that a higher CTHRC1 expression level predicts a poorer prognosis in patients with various cancers." (PMID 34702252, 2021). "These cells also displayed high CTHRC1 levels, which were shown to promote tumorigenesis, proliferation, invasion, and metastasis in several malignant tumors via different signaling pathways." (PMID 34745098, 2021). "The pan-cancer analysis showed that CTHRC1 was overexpressed in most tumors, and a significant correlation was observed between CTHRC1 expression and the prognosis of patients with cancer." (PMID 34702252, 2021). "In order to explore the relationship between CTHRC1 and available cancer therapeutic drugs, a gene–drug interaction network was developed using the CTD database." (PMID 34615943, 2021). "The single-gene GO analysis of CTHRC1 across cancers showed that it was involved in some signaling pathways and biological processes, such as the Wnt signaling pathway, cell migration, and positive regulation of protein binding." (PMID 34702252, 2021). "Then, we identified 10 genes which were positive correlated with the expression of CTHRC1 in most cancers." (PMID 34702252, 2021). "In fact, we still lack pan-cancer evidence on the relationship between CTHRC1 and multiple types of tumors." (PMID 34702252, 2021). "We have shown that CTHRC1 mRNA is abnormally regulated in various cancers, and thus we continued to explore the role of the CTHRC1 protein in cancers." (PMID 34702252, 2021). "To further explore CTHRC1 expression in human cancers, we examined CTHRC1 expression using the TIMER2 and SangerBox online databases." (PMID 34702252, 2021). "In our study, we revealed that CTHRC1 expression was elevated in 24 major subtypes of human cancers, compared to normal controls." (PMID 34615943, 2021). "TCGA data indicated that CTHRC1 gene is altered at different sites in different cancers, and the dominant alteration of CTHRC1 gene is amplification in most cancer types." (PMID 34702252, 2021). "We analyzed the differences of CTHRC1 mRNA expression levels in different cancer and normal tissues using the Oncomine database." (PMID 34702252, 2021). "Levels of CTHRC1 promoter methylation were decreased in most cancer tissues compared with normal tissues." (PMID 34702252, 2021). "By exploring the UALCAN databases, we analyzed the CTHRC1 expression across 24 different cancer tissues paired with normal samples." (PMID 34615943, 2021). "In detail, CTHRC1 (collagen triple helix repeat containing-1) is a cancer-related extracellular protein." (PMID 33800494, 2021). "We then examined the potential correlations between CTHRC1 gene expression and the level of infiltration of different immune cells in various cancers using the TIMER2 portal." (PMID 34702252, 2021). "This implies that CTHRC1 plays a significant role in the development and progression of these cancers." (PMID 34615943, 2021). "To date, few publications have provided pan-cancer insights into CTHRC1 from a holistic perspective of tumors." (PMID 34702252, 2021).
cancer (continued). "The pathways modulated by CTHRC1 reflect its role in tissue remodeling after injury, regulation of ossification and other physiological processes, most significantly cancer development and progression to metastasis." (PMID 33670905, 2021). "For this purpose, we used UALCAN, GENT2, and HPA databases, as well as the Kaplan–Meier (KM) plotter tool to analyze and validate CTHRC1 expression and its correlation with the prognosis of distinct cancer subtypes." (PMID 34615943, 2021). "It has been reported that in cancer tissue an elevated expression of collagen triple helix repeat containing 1 (CTHRC1) leads to IFNAR1/2 reduced expression and JAK/STAT signaling repression." (PMID 34681093, 2021). "CTHRC1 is a cancer-related gene that can promote cancer recurrence or metastasis via diverse signaling pathways, including TGF-β, MEK/ERK, and PKC-δ/ERK." (PMID 35004767, 2021). "Bioinformatics methods represent a beneficial approach to examine the mechanism and function of the CTHRC1 gene in the disease process of cancers from a pan-cancer perspective." (PMID 34702252, 2021). "In summary, many molecules can regulate the expression and activity of CTHRC1 and together with CTHRC1 as novel antitumor molecular targets for the treatment of cancer in the future." (PMID 32848510, 2020). "We investigated the Kaplan-Meier plotter database for the prognostic significance of CTHRC1 expression in human cancers." (PMID 33628726, 2020). "In conclusion, the negative regulation of CTHRC1 by miRNA has the potential to become a novel direction for cancer treatment in the future." (PMID 32848510, 2020). "Recently, CTHRC1 was found to be highly expressed in many human cancers, promoting invasion and metastasis." (PMID 31612481, 2020). "As Kaplan-Meier plotter analyzes only OS and RFS value, we assessed the multiple clinical prognostic value of CTHRC1 in a variety of cancers by R project using “survival” packages." (PMID 33628726, 2020). "CTHRC1 is a highly conserved cancer-secreted glycosylated protein; human CTHRC1 shares 80% sequence identity with the Gallus homolog, which was discovered in a screening for differentially expressed genes in a rat model of balloon-injured vasculature." (PMID 33102569, 2020). "The results showed that CTHRC1 was significantly high in various cancer tissues, compared to normal tissues." (PMID 33628726, 2020). "There has been a growing enthusiasm for targeting CTHRC1 in the progression and metastasis of various cancers, including NSCLC." (PMID 30469488, 2018). "In this report, CTHRC1 upregulation was associated with lymphatic metastasis, distant metastasis, and MMP7 and MMP9 overexpression in NSCLC patients, indicating CTHRC1 plays a critical role in promoting cancer invasiveness." (PMID 29631554, 2018). "CTHRC1 is widely upregulated in several solid tumours, including melanoma and cancers of the gastrointestinal tract, breast, thyroid, liver and pancreas." (PMID 29631554, 2018). "CTHRC1 (collagen triple helix repeat containing‐1), an extracellular matrix‐related secreted glycoprotein, was ubiquitously upregulated in many cancer types." (PMID 29988590, 2018). "We also show that CTHRC1 stimulated the expression of bFGF in osteoblasts through increasing Wnt/β-catenin signaling, and the cell-specific roles of bFGF and CTHRC1 in cancer and bone cells." (PMID 30469488, 2018). "Taken together, the roles of CTHRC1 and bFGF in osteoblasts, osteoclasts, and cancer cells contribute to the complexity of bone lesion development." (PMID 30469488, 2018). "In conclusion, CTHRC1 expression promoted cancer cell invasiveness and metastasis through activation of the PI3K/Akt/ERK/CREB (Snail) pathways, which induced EMT change and MMP expression." (PMID 29285247, 2017). "Growth factor-mediated CTHRC1 expression promoted cancer cell invasiveness and metastasis through activation of CREB/Snail signaling, which induced EMT change and MMPs expression." (PMID 29285247, 2017).